PTCH1 (patched 1)
Diseases named in the same sentence as PTCH1 in open-access papers (continued):
Sharing a sentence is not in itself a finding about the gene and the disease.
cancer (continued). "Therefore, the use of an inhibitor of Ptch1 drug efflux activity in combination with classical or targeted chemotherapy could be a promising therapeutic option for Ptch1-expressing cancers." (PMID 30110910, 2018). "Therefore, the use of a Ptch1 drug efflux inhibitor in combination with classical or targeted therapy could be a promising therapeutic option for Ptch1-expressing cancers." (PMID 30110910, 2018). "However, it remains unclear how Hh ligands, their receptor Ptch1 and the downstream signaling are regulated in cancer cells." (PMID 25955804, 2015). "Even in tumors with elevated expressions of the HH target genes GLI1 and PTCH1, the expression of SHH, as a canonical driver of the HH pathway, is not necessarily high, suggesting other mechanisms of HH signaling activation in cancer." (PMID 40565349, 2025). "Previous research confirmed that TSPAN8 promotes cancer cell stemness by directly interacting with PTCH1 and enhancing the stability of the SHH-PTCH1 complex." (PMID 41353440, 2025). "Homozygosity in PTCH1 (a second PTCH1 deletion, for example, from UV light damage) in BCNS is required for cancer formation, but inherited BCC accounts for 1–2% of BCC; the vast majority of BCC is sporadic." (PMID 41373535, 2025). "Genes related to cancer proliferation including NOTCH1 (p < 0.05), EP300 (n.s.), and PTCH1 (p < 0.05) were all upregulated in DR‐LSCC." (PMID 40385549, 2025). "Moreover, targeting PTCH1 may be a key strategy to overcome taxane resistance in cancer." (PMID 37700842, 2023). "As an activator of the Hedgehog pathway via miR-802/PTCH1, SNHG16 is also upregulated in cancer stem cells (CSCs)." (PMID 37600653, 2023). "SHH binds to the PTCH1 receptor expressed on the cell membrane of osteoblasts and cancer cells, to activate the SHH/PTCH1/GLI1 signaling pathway, which leads to the binding of GLI1 to the promoter of IL-6 and increases the IL-6 expression." (PMID 35285760, 2022). "The same study stated that high levels of SHH, PTCH1, and GLI2 are focally expressed in the epithelium of carcinoma in situ, suggesting potential early screening possibilities for unusual HH signaling activity." (PMID 33494284, 2021). "These implicate that S-scores and N-scores can allow one to find another type of biomarkers such as EXT1, PTCH1, KLK10, APC, TRIM13 that have strong information sensitive to early cancer." (PMID 33580150, 2021). "In these cells, TSPAN8 enhances Sonic Hedgehog (SHH) signaling, stabilizes the expression of protein patched homolog 1 (PTCH1) by recruiting ataxin-3 (ATXN3), and promotes cancer stemness." (PMID 32138170, 2020). "Expression of FOXM1 correlates directly with the expression of patched-1 (PTCH1), smoothened (SMO) and GLI1 in various cancers." (PMID 33680951, 2020). "Studies have shown that GANT61 significantly decreases the transcriptional production and gene expression of GLI1, PTCH1, and other HH pathway target genes, as evidenced by inventoried GLI assays in a range of cancer cell types." (PMID 32846867, 2020). "Similar results were observed in other human cancer lines after treatment with GANT61, with inventoried GLI assays demonstrating a reduction in gene and protein expression of the target genes GLI1 and PTCH1, as well as reduced transcriptional production." (PMID 32846867, 2020). "In the current study, we have developed a qRT-PCR method to accurately determine the expression levels of SMO, PTCH1, GLI1, GLI2, and GLI3 in a panel of cancer cell lines." (PMID 32784501, 2020). "In this study, we revealed that the residual cancer cells following treatment with chemotherapeutic reagent cisplatin have elevated expression of hedgehog target genes GLI1, GLI2 and PTCH1, suggestive of hedgehog signaling activation." (PMID 28404967, 2017).
cancer (continued). "Moreover, genes related to cancer therapeutic targets, such as ABCG2, GSK3B, PTCH1, STAT3 and WEE1, were also upregulated." (PMID 39726234, 2025). "The PTCH1 gene, responsible for NBCCS, suppresses the hedgehog signaling pathway, which is recognized as one of the important pathways in tumorigenesis and, thus, is a therapeutic target in cancer." (PMID 35618979, 2022). "It cannot be compared with PTCH1 PV carriers since such an evaluation of cancer incidence in relatives is not available in this population." (PMID 35768194, 2022). "Intriguingly, stabilization of Ptch1 by TSPAN8 promoted Ptch1 exit from and Smo accumulation in primary cilia, resulting Hh pathway activation, which was thought to mediate the role of TSPAN8 in promoting cancer stemness and chemotherapy resistance." (PMID 34948134, 2021). "There are two classes of Gli-independent, non-canonical Hh signaling in cancers: type I, which works through Ptch1 and is independent of Smo, and type II, which functions through Smo activation." (PMID 30110910, 2018). "Moreover, the role of few important proteins has been identified in this pathway, such as PTCH1, SMO, GLI etc., which are mainly responsible for the malfunctioning of this pathway in various types of cancers." (PMID 23935937, 2013). "Indeed, we here show that PDGFRα and essential components of the Hh pathway, including SMO, PTCH1 and GLI2, localize to primary cilia of wt OSE cells and that cancer OSE cells display increased basal expression of Hh responsive genes." (PMID 23351307, 2012). "PTCH1 was not positively correlated with any DE genes in cancer." (PMID 33580150, 2021). "The protein levels of Gli1, Ptch1, and SMO were examined after itraconazole treatment, and signals decayed after peak in endothelial cells, which was not shown in cancer cell." (PMID 28747628, 2017). "HIP1 expression was only detected in 2 specimens which expressed PTCH1 or Gli1, indicating that HIP1 is not highly expressed in ovarian tissues or is silenced in cancers as reported in other studies." (PMID 19943941, 2009). "Besides the classical canonical ligand-PTCH1-SMO route, mounting evidence points toward additional, non-canonical ways of GLI activation in cancer." (PMID 31244888, 2019). "Indeed, except for that PTCH1, KLK10, TBRG1, NBL1 and EXT1 did not act on gene expression in stage-2 cancer, the other 21 TS gene had larger positive network effects on gene expression than negative network effects in cancer." (PMID 33580150, 2021).
infection (5 papers, 2005 to 2022). The state of being infected such as from the introduction of a foreign agent such as serum, vaccine, antigenic substance or organism. "Since endogenous Ptch1 protein was difficult to detect in NIH 3T3 cells by antibody staining, we utilized Ptch1-YFP MEFs generated by infection of Ptch1LacZ/LacZ mutant cells with a retrovirus expressing a Ptch1-YFP fusion protein." (PMID 25936505, 2015). "As seen in wild-type cells, infection of Tg737Δ2–3β-gal primary limb cells with full-length Gli1 resulted in increased transcription of Ptch1 compared to infection with green fluorescent protein (GFP)–only virus." (PMID 16254602, 2005). "However, infection of Tg737Δ2–3β-gal primary limb bud cells with Gli2-expressing virus failed to induce Ptch1 transcription suggesting that Gli2 function requires the activity of Polaris." (PMID 16254602, 2005).
cardiovascular diseases (2 papers, 2018 to 2024). "Results from these experiments showed downstream HH signaling proteins such as PTCH1, SMO, GLI 1, GLI 2 and GLI 3 to be functionally impaired, indicating impairment of SHH signaling pathway in cardiovascular diseases." (PMID 30301174, 2018).
CNS tumor (2 papers, 2018 to 2025). "Comparative molecular analysis between the primary CNS tumor and relapsing bone and epidural metastases showed a similar PTCH1 mutated profile." (PMID 29515801, 2018). "Retrospective immunohistochemical analysis of the primary CNS tumor showed the SHH-MB immunophenotype, which was further confirmed by retrospective CGH array and targeted next-generation sequencing showing chromosome 9q copy neutral-loss of heterozygosity and the PTCH1 mutation, respectively." (PMID 29515801, 2018).
adenocarcinoma (1 paper, 2017). A common cancer characterized by the presence of malignant glandular cells. "We also found that Sufu knockdown reduced Hh downstream target genes Gli and Ptch1 in cervical squamous cell lines (SiHa and HCC94) rather than in adenocarcinoma cell line (HeLa)." (PMID 29371981, 2017).
neurodegenerative disease (1 paper, 2024). A disorder of the central nervous system characterized by gradual and progressive loss of neural tissue and neurologic function. "Of the 619 detected genes, 227 have previously been implicated in cognitive function, education, neuroticism, neuropsychiatric disorders, neurodegenerative diseases, and reaction time, such as ARIH2 and PTCH1." (PMID 38190638, 2024).
PTCH1 also shares sentences with these, for which no sentence is quoted: genetic disorder (4 papers); acute myeloid leukemia (3); autosomal dominant disease (3); cerebellar tumors (3); jaw cysts (3); leukemia (3); lymphoma (3); myeloid leukemia (3); cirrhosis of the liver (2); Cowden syndrome (2); invasive breast carcinoma (2); neurofibroma (2); nevus (2); soft tissue neoplasm (2); stomach adenocarcinoma (2); triple-negative breast carcinoma (2); acute promyelocytic leukemia (1); anaplastic astrocytoma (1); astrocytic tumor (1); autosomal dominant polycystic kidney disease (1); basal cell tumors (1); benign neoplasm (1); bladder urothelial carcinoma (1); blepharocheilodontic syndrome (1); Cerebellar medulloblastoma (1); cerebral artery (1); childhood cancer (1); Chronic colitis (1); chronic hepatitis (1); CLIFAHDD syndrome (1).
A further 61 diseases each share a sentence with PTCH1 in 1 paper.